EZH2 (enhancer of zeste 2 polycomb repressive complex 2 subunit)
Diseases named in the same sentence as EZH2 in open-access papers (continued):
Sharing a sentence is not in itself a finding about the gene and the disease.
bone tumors (3 papers, 2021 to 2024). "Together, our data demonstrate that EZH2-mediated downregulation of SULF1 is critical for de-suppressed cMET signaling pathway in bone cancer." (PMID 36622753, 2023). "Knockdown of EZH2 and P100-α genes causes suppression of bone tumors without eliciting an auto-immune response." (PMID 38255196, 2024). "To further validate our observation in clinical setting, we examined the clinical significance of EZH2, SULF1, and phospho-cMET by analyzing H-score of immunohistochemistry (IHC) on commercially available human bone cancer tissue array." (PMID 36622753, 2023).
diffuse intrinsic pontine glioma (3 papers, 2017 to 2024). A neuroglial tumor that arises from the middle portion of the brain stem. "Even in cells derived from diffuse intrinsic pontine gliomas (DIPG), a brain pediatric cancer that can also affect young adults, in which the actions of EZH2 are inhibited by the H3K27M mutation, residual EZH2 activity is still retained at strong PRC2 targets to drive GSC proliferation." (PMID 33344253, 2020).
epilepsy (3 papers, 2019 to 2023). A brain disorder characterized by episodes of abnormally increased neuronal discharge resulting in transient episodes of sensory or motor neurological dysfunction, or psychic dysfunction. "The genes were chosen on the basis that they important functions in glutamatergic and GABAergic signaling, have been implicated in epilepsy disease pathology, Factor analysis tagged them as EZH2 targets and were repressed at 1d, 3d and 10d post SE across models in the EMC dataset." (PMID 31891591, 2019). "A prototype of the MAGIC approach was recently used to identify EZH2 as a principle driver of gene changes in epilepsy." (PMID 32251445, 2020). "In this study, we find that EZH2 is up-regulated after SE in multiple rodent epilepsy models and provide evidence suggesting that EZH2 function is increased in human TLE." (PMID 31891591, 2019). "Overall, our analysis reveals that there is a distinct gene module regulated by EZH2 in rodent and human epilepsy." (PMID 31891591, 2019). "Nevertheless, the approach identified EZH2 as a robustly induced cofactor across multiple epilepsy models and human TLE." (PMID 31891591, 2019). "We identified EZH2 through mining a dataset provided by the Epilepsy Microarray Consortium that consists of transcriptome data from 3 epilepsy models across 11 laboratories." (PMID 31891591, 2019). "We find that Enhancer of Zeste Homolog 2 (EZH2) regulates differentially expressed genes in epilepsy across multiple rodent models of acquired epilepsy." (PMID 31891591, 2019). "This is the first study to identify a role for EZH2 in controlling disease progression and uncovers an innate protective mechanism in epilepsy." (PMID 31891591, 2019). "Future work will follow how EZH2 levels and function may change as animals transition from the latent to chronic phase marked by spontaneous behavioral seziures and may shed light in the presence of an EZH2 signature in human epilepsy samples." (PMID 31891591, 2019). "It is tempting to speculate that EZH2 upregulation in epilepsy may be an attempt to modify synaptic transmission as a protective strategy that is ultimately overwhelmed." (PMID 31891591, 2019).
essential thrombocythemia (3 papers, 2017 to 2025). A chronic myeloproliferative neoplasm that involves primarily the megakaryocytic lineage. "This contrasts with the single KO mice in which Asxl1 KO mice were largely normal with mild polycythemia vera–like or essential thrombocythemia–like hematopoietic phenotypes noted in some animals, whereas Ezh2 KO resulted in low penetrant MDS/MPN LPDs with extended disease latency." (PMID 40561338, 2025).
Fulminant hepatic failure (3 papers, 2020 to 2024). Hepatic failure refers to the inability of the liver to perform its normal synthetic and metabolic functions, which can result in coagulopathy and alteration in the mental status of a previously healthy individual. "Similarly, EZH2 can be enriched in the LATS2 promoter region to affect its expression through H3K27me3 in fulminant hepatic failure." (PMID 38652219, 2024). "Importantly, evidence supports that EZH2 can be recruited into the promoter of LATS2 to augment H3K27me3 methylation, thus restraining LATS2 expression in fulminant hepatic failure." (PMID 38652219, 2024).
gynecologic cancer (3 papers, 2017 to 2025). "The potential therapeutic role of EZH2 inhibition in ARID1A mutated gynecologic cancers may represent a novel and exciting treatment paradigm in a subset of patients with limited treatment options." (PMID 29093822, 2017). "In summary, EZH2 inhibitors hold transformative potential in gynecological cancer therapy by reshaping the TIME and augmenting immunotherapy." (PMID 41029427, 2025). "Epigenetic regulation plays a pivotal role in the carcinogenesis of gynecological cancers, with Enhancer of zeste homolog 2 (EZH2) emerging as a critical epigenetic modulator." (PMID 41029427, 2025). "Within the gynecologic cancer arena, the predominant mechanisms are EZH2 overexpression and SWI/SNF antagonism of the Polycomb complex." (PMID 29093822, 2017). "Thus, EZH2 inhibitors not only disrupt tumor-intrinsic pathways but also restore immune homeostasis, offering a multifaceted approach to combat gynecological cancers." (PMID 41029427, 2025). "Beyond intrinsic epigenetic modulation, EZH2 inhibitors significantly enhance the efficacy of adoptive T cell therapies, such as CAR-T and TCR-T cells, in gynecological cancers." (PMID 41029427, 2025).
HIV-1 infection (3 papers, 2017 to 2025). The type species of lentivirus and the etiologic agent of acquired immunodeficiency syndrome (AIDS). "Notably, 3-deazaneplanocin A (DZNep), an EZH2 inhibitor, has been proven to effectively activate latent HIV-1 infection in CD4+ T cells and Jurkat T cells (75, –, 78)." (PMID 39692477, 2025).
Hodgkins lymphoma (3 papers, 2023 to 2025). A heterogeneous group of malignant lymphoid neoplasms of B-cell origin characterized histologically by the presence of Hodgkin and Reed-Sternberg (HRS) cells in the vast majority of cases. "The cytotoxic effects of the EZH2 degrader and EZH2 inhibitor were evaluated in Burkitt’s, B-cell, cutaneous T-cell, and Hodgkin’s lymphoma cell lines." (PMID 40308579, 2025).
Insulin resistance (3 papers, 2018 to 2025). Increased resistance towards insulin, that is, diminished effectiveness of insulin in reducing blood glucose levels. "In addition to Sirtuins, there are other epigenetic modification enzymes, including SUV39H1 and EZH2 are involved in insulin resistance and T2DM." (PMID 30574122, 2018).
Kaposi's sarcoma (3 papers, 2014 to 2021). A malignant neoplasm characterized by a vascular proliferation which usually contains blunt endothelial cells. "In Kaposi sarcoma, KSHV-mediated upregulation of EZH2 was required for the induction of Ephrin-B2, an essential pro-angiogenic factor which drove endothelial cell tube formation." (PMID 25237831, 2014).
latent infection (3 papers, 2017 to 2024). "CMV latent infection associated hyper-methylated CpG sites are enriched in PcG proteins including RNF2, EZH2, KDM2B and JARID2." (PMID 39360678, 2024). "First, it was shown the H3K27 methyltransferase EZH2 was recruited to the major IE promoter (MIEP) in CD14+ monocytes where hCMV establishes latent infection in vivo, resulting in increased H3K27Me3 mark at the MIEP region." (PMID 28407004, 2017). "Moreover, actively proliferating cell subsets in early and latent infection contexts have EZH2, TCF3, and BRCA1 expression signatures as observed in proliferating DZ B cells in vivo." (PMID 38059622, 2024).
leiomyosarcoma (3 papers, 2020 to 2024). An uncommon, aggressive malignant smooth muscle neoplasm, usually occurring in post-menopausal women. "In addition, it has been shown that EZH2 inhibition is able to suppress leiomyosarcoma CSCs proprieties and retrieve the anti-tumor effect of PI3K/mTOR inhibition, supporting the therapeutic value of this combination." (PMID 32532153, 2020).
lentivirus infection (3 papers, 2018 to 2019). Virus diseases caused by the Lentivirus genus. "According to Western blot analysis, the H3K27me3 level was increased through the lentivirus infection, which also validated the EZH2-overexpressing efficiency of the vector used." (PMID 31511494, 2019). "The EZH2 expression level and methylation of H3K27 were verified by western blots, and the results showed that EZH2 protein levels and H3K27me3 were significantly reduced after shEZH2-1 lentivirus infection, while the knockdown efficiency of shEZH2-2 was less than satisfactory." (PMID 29416002, 2018).
liposarcoma (3 papers, 2016 to 2024). A usually painless malignant tumor that arises from adipose tissue. "The data set GDS2736 showed the expression level of EZH2 mRNA in LMS (n = 6) was higher than that in well-differentiated liposarcoma (n = 3) (p < 0.05)." (PMID 30120321, 2018).
malignant pleural mesothelioma (3 papers, 2023 to 2025). A malignant neoplasm that arises from mesothelial cells in the pleura and shows a diffuse growth pattern. "In malignant pleural mesothelioma, EZH2 inhibition activates monocyte differentiation into the TAM phenotype, further promoting mesenchymal stem cell growth and extracellular matrix remodeling, which contributes to high invasion rates and poor survival." (PMID 40042761, 2025). "While EZH2 inhibitors show promise in malignant pleural mesothelioma treatment, their effectiveness is limited by MSC-mediated oncogene activation, suggesting that targeting monocyte recruitment and depleting TAMs may restore the antitumor activity of EZH2 inhibitors." (PMID 40042761, 2025).
neuroendocrine carcinoma (3 papers, 2019 to 2022). A malignant neuroendocrine neoplasm composed of cells containing secretory granules that stain positive for NSE and chromogranin. "Here, we demonstrate that IGF2BP1 promotes proliferation of neuroendocrine cancer cells by regulating the histone-lysine N-methyltransferase Enhancer of Zeste homolog 2 (EZH2) at the post-transcriptional level." (PMID 35565249, 2022). "CpGs of lower methylation in VP-MCC cell lines were associated with neuroendocrine marker genes such as SOX2 and INSM1, or linked to binding sites of EZH2 and SUZ12 of the polycomb repressive complex 2, i.e., genes with an impact on carcinogenesis and differentiation of neuroendocrine cancers." (PMID 34667274, 2022). "Moreover, pharmacological inhibition of IGF2BP1-mediated EZH2 expression led to cell cycle arrest and apoptosis induction in neuroendocrine cancer cell lines." (PMID 35565249, 2022).
neurofibroma (3 papers, 2017 to 2023). An intraneural or extraneural neoplasm arising from nerve tissues and neural sheaths. "Nuclear EZH2 levels were reported to be induced in MPNST compared to neurofibromas and normal nerves as measured by immunohistochemistry." (PMID 28813519, 2017). "Our observations support these results as the EZH2 mRNA levels were significantly increased in the MPNST samples from 6 out of 9 plexiform neurofibroma/MPNST pairs." (PMID 28813519, 2017). "Similarly, all the MPNST cell lines displayed relatively high EZH2 mRNA levels compared to the neurofibroma cell line." (PMID 28813519, 2017). "In addition, also enhancer of zeste homolog 2 (EZH2) was found upregulated in MPNST compared to neurofibroma and normal nerves." (PMID 28813519, 2017). "The transcript levels of BRD4, EZH2 and TOP2A were determined in paired formalin-fixed paraffin-embedded (FFPE) neurofibroma/MPNST samples derived from the same NF1 patient and in a set of plexiform neurofibromas, atypical neurofibromas and MPNST." (PMID 28813519, 2017). "In this study we analyzed the expression level of three potential drug targets BRD4, EZH2, and TOP2A in selected human MPNST and neurofibroma samples from the Erasmus MC tissue bank." (PMID 28813519, 2017). "We do confirm that EZH2, at least at the mRNA level, is more abundantly expressed in MPNST than in plexiform neurofibromas." (PMID 28813519, 2017). "Also in RNA isolated from fresh frozen neurofibroma and MPNST samples EZH2 mRNA levels appeared on average to be 8-fold higher in MPNST than in (atypical) plexiform neurofibromas." (PMID 28813519, 2017).
oropharyngeal squamous cell carcinoma (3 papers, 2017 to 2023). "Furthermore, overexpression of EZH2 is correlated with inferior patient outcomes in HPV-positive oropharyngeal squamous cell carcinoma (OPSCC), also making EZH2 a particularly attractive epigenetic therapeutic target in this cancer type." (PMID 37298494, 2023).
parathyroid tumors (3 papers, 2021 to 2024). "Mutations on CDC73, MEN1, HIC1, EZH2, and β-catenin genes, demonstrated to be involved in parathyroid tumors, seem to implicate epigenetic modifications in their mechanism of tumorigenesis." (PMID 35628190, 2022). "For the patients with parathyroid neoplasms (PC, APT and PA), higher serum iPTH was associated with Ki-67 > 5% (P = 0.035), positive EZH2 (P < 0.001), galectin-3 (P = 0.002) and PGP9.5 staining (P = 0.027)." (PMID 38340242, 2024). "It was proposed that EZH2 overexpression was involved in important pathways of parathyroid tumor development." (PMID 38340242, 2024). "Previously, we have shown that in parathyroid tumors, EZH2 is overexpressed and may have a crucial role in parathyroid tumorigenesis." (PMID 34815475, 2021). "EZH2 is overexpressed in parathyroid tumors regardless of their malignant or benign origin." (PMID 35628190, 2022).
pituitary adenomas (3 papers, 2015 to 2023). "EZH2 has several actions in human pituitary adenomas (PAs), regulating cell proliferation and apoptosis, development, and differentiation." (PMID 37445833, 2023). "This indicates a possible function of EZH2 in pituitary regulation and homeostasis, which is consistent with previous findings where there were greater abundances of this transcript in pituitary adenomas." (PMID 37445833, 2023).
preeclampsia (3 papers, 2019 to 2023). Preeclampsia is a hypertensive disorder of pregnancy that is characterized by new-onset hypertension with proteinuria presenting after 20 weeks of gestation, and depending on mild or severe forms may initially present with severe headache, visual disturbances, and hyperreflexia. "While TUG1 downregulation boosted the expression of the enhancer of zeste homolog 2 (EZH2) and decreased the levels of the Rho family GTPase 3 (RND3) in Preeclampsia, it prevented remodeling of the uterine spiral artery." (PMID 37745705, 2023).
pulpitis (3 papers, 2020 to 2026). Inflammation of the dental pulp. "In recent years, many studies have found that EZH2 can play important roles in various inflammatory diseases such as lupus-like diseases, dental pulp inflammation, and neuropathic pain by promoting the expression of macrophage chemokine CCL2." (PMID 34899918, 2021). "Previous studies have confirmed that EZH2 can promote the progress of dental pulp inflammation by regulating the expression of cytokines in vitro." (PMID 34899918, 2021). "In our study, we explored the chemotactic effects of EZH2 on macrophages and anti-inflammatory genes in dental pulp inflammation." (PMID 34899918, 2021). "This study further confirmed that EZH2 participates in the development of dental pulp inflammation through in vivo and in vitro experiments." (PMID 34899918, 2021). "Using a rat pulpitis model, the authors also showed reduction of pulpitis responses in the animals exposed to DZNep, a pharmacological inhibitor of EZH2, further demonstrating the physiological role of EZH2 in pro-inflammatory signaling in dental pulp." (PMID 32116745, 2020). "EZH2 could affect the production of inflammatory/chemokines, immune regulatory functions, and process of the pulpitis." (PMID 34899918, 2021). "Therefore, the mechanism of EZH2 promoting macrophage chemotaxis in pulpitis needs further exploration." (PMID 34899918, 2021). "The reduced expression of EZH2 in the early period of dental pulp inflammation may be related to the mechanism of repair in the early stage of dental pulp inflammation." (PMID 34899918, 2021). "So, we hypothesize that EZH2 might modulate the migration of macrophages in dental pulp inflammation." (PMID 34899918, 2021). "It is speculated that the effect of EZH2 on dental pulp inflammation might include microphage chemotaxis." (PMID 34899918, 2021). "Previous studies have shown that EZH2 promoted the progress of dental pulp inflammation." (PMID 34899918, 2021). "EZH2 plays an important role in the development of dental pulp inflammation, and it might be as a target for treatment of pulpitis." (PMID 34899918, 2021). "However, the mechanism of EZH2 in pulpitis is still unclear." (PMID 34899918, 2021). "And it might indicate that EZH2 might have important roles in regulating pulpitis." (PMID 34899918, 2021). "Immunohistochemistry staining was used to detect changes of the expression of EZH2 and tumor necrosis factor alpha (TNF-α) in dental pulp inflammation." (PMID 34899918, 2021). "We aimed to evaluate the effects of Enhancer of Zeste Homolog 2 (EZH2) on regulation of macrophage migration and expression of anti-inflammatory genes in pulpitis." (PMID 34899918, 2021). "EZH2 might activate the macrophage chemotaxis and affect the transcription of anti-inflammatory factors via regulating the expression of CCL2 in the process of dental pulp inflammation." (PMID 34899918, 2021).
retinal degeneration (3 papers, 2016 to 2021). Degeneration of the retina. "Our study showed that the pathological EZH2 hyperactivity observed during retinal degeneration appears to markedly alter photoreceptor survival." (PMID 34502238, 2021). "Altogether, these results reveal successive emergences of H3K27me3h and CDK4 prior cell death (TUNEL positive) suggesting that EZH2 is involved in an intermediate stage of retinal degeneration." (PMID 34502238, 2021). "EZH2 hyperactivity was observed in four recessive and two dominant mouse models of retinal degeneration, as well as two dog models and one IRD patient." (PMID 34502238, 2021). "Collectively, these data strongly suggest that EZH2 contributes to the process of cell death and that inhibiting EZH2 activity in vivo delays photoreceptor degeneration in mouse models of retinal degeneration." (PMID 34502238, 2021). "In this study, we demonstrated that histone trimethylation also increases in rd1 mice, suppression of Ezh2 and H3K27me3 by DZNep delays the retinal degeneration." (PMID 29472543, 2018). "Different models of retinal degeneration were analyzed to determine whether EZH2 activity is common to different disease forms." (PMID 34502238, 2021). "Taken together, these findings provide new insights into how dysregulation of Ezh2 function in development may contribute to retinal degeneration in postnatal life." (PMID 27677711, 2016). "Thus, Ezh2 deletion driven by Chx10-Cre results in gene expression changes that occur likely at the nexus point of cell proliferation and differentiation, persisting into adulthood, and lead to postnatal retinal degeneration." (PMID 27677711, 2016). "Ezh2, although enriched in the embryonic retina, was not present in the mature retina; these data reveal an Ezh2-mediated feed-forward pathway that is required for maintaining photoreceptor homeostasis in the adult and suggest novel targets for retinal degeneration therapy." (PMID 27677711, 2016).